TNF (tumor necrosis factor)
Diseases named in the same sentence as TNF in open-access papers (continued):
Sharing a sentence is not in itself a finding about the gene and the disease.
Insulin resistance (continued). "Insulin resistance involves important factors such as tumor necrosis factor (TNF)-α and adiponectin, which is secreted from fat cells and is one of the causes of type 2 diabetes." (PMID 33390816, 2021). "PTSD is associated with low-density lipoprotein-cholesterol, cortisol, interleukin (IL)-2, IL-6, IL-8, leptin, insulin resistance, and tumor necrosis factor (TNF)-α9–12." (PMID 33674663, 2021). "Several adipokines such as TNFα, adiponectin, leptin, and PEDF have been implicated as potential mediators of insulin resistance, both local and systemic." (PMID 34045558, 2021). "The expression of visfatin is regulated by several cytokines such as tumoral necrosis factor-alpha (TNF α), interleukin-6 (IL-6), and lipopolysaccharide that are known to promote insulin resistance." (PMID 34300193, 2021). "Thereby resulted in an increase in proinflammatory adipokines, including tumor necrosis factor-alpha and interleukins 6 and 8, leading to insulin resistance, impaired relaxation, and vascular stiffness." (PMID 33923481, 2021). "TNF-α also, stimulates ceramide accumulation through sphingomyelinase activation, while, ceramide in turn, mediates TNF-α-induced insulin resistance in adipocytes." (PMID 33584134, 2021). "The current study examines the interactions between the apM1 +45 genotypes, TNF-α -308 genotypes, and insulin resistance on the occurrence of MetS." (PMID 33997011, 2021). "Studies show that TNF-α incubation inhibits insulin-stimulated glucose uptake and leads to insulin resistance in adipocyte cell lines." (PMID 34717724, 2021). "Targeted mutations to abolish the function TNF-α receptors and expression of TNF-α improved insulin signaling in obese mice, suggesting TNF-α is critical for the development of insulin resistance." (PMID 33716966, 2021). "Decreased adiponectin and insulin resistance correlate with an increased release of other cytokines and adipokines, including TNFα and IL-6." (PMID 33799622, 2021). "TNF-α, one of the most commonly studied cytokines in relation to insulin resistance, has been shown to inhibit insulin receptor signaling." (PMID 34078385, 2021). "The ability of DHM to improve TNFα-induced insulin resistance was blocked by inhibiting AMPK, as shown by the glucose uptake assay." (PMID 34650665, 2021). "The high TNF‐α level is a critical common characteristic in insulin resistance in adipocytes and peripheral tissues by destroying the insulin signaling that resulting in the development of T2D." (PMID 34272768, 2021). "Aim of this study was to evaluate lemon extract capability to restore adipocyte functions and insulin sensitivity in a model of TNF-α-induced insulin resistance." (PMID 34361563, 2021). "Adipo-myokines, such as IL-6 and TNF-α, secreted from muscle cells and adipocytes, if chronically elevated, can induce insulin resistance and consequently other comorbidities." (PMID 33807959, 2021). "The elevation of PTP1B in the liver of obese mice, caused by the administration of Tumor Necrosis Factor-alpha (TNF-α), culminated in severe insulin resistance." (PMID 34203825, 2021). "JTP-96193 reduced the TNF release from fat tissue preventing diabetes development and improving the insulin resistance." (PMID 33579029, 2021). "Afterward, we investigated the effects of BBR combined with Rb1 on cell proliferation, inflammation state, adipogenesis, and insulin resistance in TNF-α-treated adipocytes." (PMID 34699329, 2021). "When ryanodine blocked the ryanodine receptor, the ability of DHM to improve TNF‐α‐induced insulin resistance disappeared, as shown by the glucose uptake assay." (PMID 34676967, 2021). "By directly targeting the intracellular insulin signal transduction system, TNF-α can enhance insulin resistance through upregulating suppressor of cytokine signaling 3 (SOCS-3) and inhibiting adiponectin activity." (PMID 33505505, 2021). "Adiponectin decreases and TNFα increases in NAFLD and these two events are associated with insulin resistance." (PMID 34094026, 2021).
Insulin resistance (continued). "In particular, high expression of HSP60 induces the release of IL-6 and TNF-α by adipocytes, contributing to the onset of insulin resistance." (PMID 34206506, 2021). "A high level of endotoxemia has been found to increase the concentrations of tumour necrosis factor α (TNF-α) and interleukin 6 (IL-6) and the promotion of insulin resistance." (PMID 34073366, 2021). "Like TNF-α, IL-6 also promotes insulin resistance by attenuating the expression of IRS-1 and GLUT-4 and deregulating fatty acid metabolism in adipocytes." (PMID 33917607, 2021). "Inflammation, together with insulin resistance, is increased by expression of several pro-inflammatory cytokines such as interleukin IL-1, IL-6, and tumor necrosis factor (TNF-α)." (PMID 33918576, 2021). "PP4R1 is one of the regulatory subunits of PP4, it is considered to be a regulator of TNF-α-induced hepatic insulin resistance." (PMID 33750415, 2021). "Its overexpression reduces the secretion of IL1β, IL6 and TNFα in lipopolysaccharide-stimulated macrophages, preventing macrophage-mediated adipose tissue inflammation and improving insulin resistance." (PMID 34943849, 2021). "This induces the expression of inflammatory cytokines such as tumor necrosis factor α (TNF-α) and interleukin 6 (IL-6), contributing to inflammation and insulin resistance, which can increase fat accumulation in the liver." (PMID 34441497, 2021). "Several parameters including blood glucose, lipid profile, CRP, TNF-α, IL-10, and insulin resistance (IR) were measured over the whole study period." (PMID 35096939, 2021). "H-Exo vs L-Exo treatment resulted in the induction of an array of inflammatory cytokines detected in the plasma and WAT, including TNF-α and IL-6, which are known to contribute to insulin resistance." (PMID 33431899, 2021). "Chronic inflammation in both PsA and atherosclerosis promotes increased production of adipokines and pro-inflammatory cytokines (e.g., TNF) with consequent insulin resistance and endothelial dysfunction." (PMID 34631754, 2021). "Insulin resistance, TNF and estrogen promote the progression of HCC, and these factors are attracting increased attention from researchers." (PMID 34671598, 2021). "We have previously found that long-term fructose-induced hepatic insulin resistance was reversed in concomitance with normalization of plasma levels of LPS and TNFα." (PMID 33921866, 2021). "Among the proinflammatory cytokines that induce insulin resistance, tumor necrosis factor α (TNFα) is the most representative one." (PMID 34650665, 2021). "NF-κB and JNK, they, in turn, inhibited IRS-1 and AKT, indicating that TNFα induced insulin resistance." (PMID 34650665, 2021). "The proinflammatory cytokine tumor necrosis factor (TNF) is known to trigger insulin resistance and exacerbate the accumulation of amyloid beta in AD models." (PMID 33643025, 2021). "The present study tests the interactions between the apM1 +45 genotypes, TNF-α -308 genotypes, and insulin resistance on the occurrence of Taiwanese MetS." (PMID 33997011, 2021). "Production of TNF-α by ILC1s would lead to further exacerbation of insulin resistance which has a variety of downstream consequences for insulin signaling." (PMID 34489979, 2021). "The pathogenic mechanisms of cardiometabolic comorbidities in psoriasis patients involve common genetic factors, lipid metabolism, insulin resistance, and shared inflammatory pathways such as tumor necrosis factor-α and interleukin-23/Th-17 pathways." (PMID 34803716, 2021). "In fact, obese patients with insulin resistance had systemic arterial dysfunction concurrent with high M1 ATMs and TNFα mRNA in SAT and elevated serum C reactive protein (CRP), indicating a proinflammatory state." (PMID 33897419, 2021). "Excess MCP-1 and inflammatory cytokines including TNF-α secreted from infiltrated macrophages, induce additional infiltration of macrophages and insulin resistance, respectively." (PMID 33494317, 2021).
Insulin resistance (continued). "It has been shown that TNF-α leads to insulin resistance, which increases the release of FFA, the accumulation of which in cardiomyocytes leads to their lipotoxic damage." (PMID 34088886, 2021). "Innate immunity activation results in the production of like tumor necrosis factor-alpha (TNF-α), create a connection between the inflammation and the components of MetS like central adiposity, insulin resistance (IR), and different other impediments." (PMID 34104151, 2021). "Tumor necrosis factor-α (TNF-α) has a pivotal role in insulin resistance as its concentrations are raised in GDM." (PMID 33918528, 2021). "This type of macrophages induces inflammation and insulin resistance by secreting the proinflammatory cytokines, including tumor necrosis factor α (TNF-α), and the interleukins IL-6, IL-12, and IL-23." (PMID 34769133, 2021). "When fat storage is increased, blood monocytes are attracted to the fat tissue forming resident macrophages, which in turn produce the proinflammatory cytokine TNFα leading to insulin resistance and glucose intolerance." (PMID 34306160, 2021). "Noticeably, TNFα, IL-1β, IL-18, and IL-6 are the most important cytokines involved in the development of insulin resistance." (PMID 34070553, 2021). "Such alterations in the adipose tissue lead to adipocyte hypertrophy, immune cell infiltration, and increased cytokine (IL-1β, IL-6, TNFα) and chemokine production, which eventually lead to insulin resistance, T2DM, dyslipidemia, and hypertension." (PMID 34299302, 2021). "Aggravation of glucose intolerance, insulin resistance, deposits of Aβ, and hallmarks of neuroinflammation such as tumor necrosis factor (TNF)-α, interleukin (IL)-1β, and cyclooxygenase-2 were observed in the generated mice." (PMID 33669988, 2021). "In contrast to the expression of adipokines such as TNF‐α and MCP‐1, which causes insulin resistance, Adiponectin expression is reduced in obese, insulin‐resistant rodent models." (PMID 33314576, 2021). "TNF-α induced insulin resistance in an enterocyte cell line of IEC-18 cells, and BME promoted glucose utilization of the insulin-resistant cells." (PMID 33746602, 2021). "It is also well documented that increased adipocyte leads to over production of TNF-alpha, instigating insulin resistance and diabetes." (PMID 35008824, 2021). "Chemical inhibition of CTH with PPG and β-cyano-L-alanine attenuated TNF-α-induced insulin resistance in 3T3-L1 adipocytes." (PMID 33919190, 2021). "Studies on synthetic PPAR antagonist showed that blocking or reducing the activity of PPARγ can reduce HFD-induced adipocyte hypertrophy and insulin resistance by reducing the size of adipocytes and decreasing the secretion of TNF-α and leptin." (PMID 34721992, 2021). "In PCOS patients, high TNF-α levels not only inhibit follicular growth but also increase insulin resistance." (PMID 33825169, 2021). "Lastly, the regulatory mechanisms underlying the effects of BBR+Rb1 on cell proliferation, inflammation, adipogenesis, and insulin resistance in the TNF-α-treated adipocytes were studied by introducing RANKL, which is an agonist of the NF-κB pathway." (PMID 34699329, 2021). "When the cells were exposed to TNF-α for a sufficiently long time (18 h) to induce insulin resistance, the insulin-stimulated uptake of glucose was downregulated by 75% (bar 3 vs. 2, p < 0.05)." (PMID 34680177, 2021). "Galantamine significantly inhibited TNF and leptin—two key mediators of the chronic inflammatory state and contributors to insulin resistance." (PMID 33776997, 2021). "Administration of TNF-alpha in mice induces insulin resistance, while attenuation of TNF-alpha with genetic or pharmacologic manipulation protects against metabolic dysfunction." (PMID 34760952, 2021). "Obesity results in insulin resistance, vitamin D deficiency, and increased expression of fibrogenic factors including TGF-β, and proinflammatory cytokines such as TNF-α and C-reactive protein; these changes cause pulmonary fibrosis." (PMID 35115954, 2021).
Insulin resistance (continued). "Previous researchers have verified that the decline in the PI3K/Akt pathway following insulin resistance leads to microglial activation and stimulation of the NF-kB signal, which provokes the generation of proinflammatory cytokines such as TNF-α and IL6." (PMID 34366841, 2021). "Hepatic cells are sensitive to circulatory TNFα and can impair the canonical insulin signaling pathway, inhibiting glucose uptake and leading to the development of insulin resistance, which precedes type 2 diabetes mellitus." (PMID 34576943, 2021). "The cytokines involved in the pathogenesis of RA, in particular TNFα, IL-1 and IL-6, also promote the development of insulin resistance." (PMID 33995414, 2021). "The increased macrophages secrete numerous cytokines and chemokines, such as TNF-α, IL-1, and IL-6, and these cytokines lead to insulin resistance." (PMID 34867288, 2021). "According to previous studies, low levels of leptin and high levels of TNF-α lead to insulin resistance." (PMID 34922625, 2021). "Ablation of TIMP-3 in mouse, and subsequent loss of ADAM17 inhibition, leads to arthritis, chronic hepatic inflammation, insulin resistance, and liver/heart failure due to excessive release of tumor necrosis factor (TNF)." (PMID 33673623, 2021). "L. plantarum MTCC5690 and L. fermentum MTCC5689 were shown to alleviate insulin resistance in mice by reducing the expression of TNF and other genes, thereby preventing the development of diabetes." (PMID 35010205, 2021). "Activation of TNF-α triggers insulin resistance by increasing uptake of glucose in visceral and subcutaneous adipocytes and through phosphorylation of serine 307 in IRS-1." (PMID 33986669, 2021). "2-AG can activate AMPK by stimulating cannabinoid type-1 receptor (CB1) and Ca2+/calmodulin-dependent protein kinase β (CaMKK β), inhibit insulin resistance induced by TNF α, improve glucose uptake, and improve diabetes mellitus." (PMID 34771066, 2021). "When STO-609 blocked CaMKK activity, the ability of DHM to improve TNFα-induced insulin resistance disappeared, as shown by the glucose uptake assay." (PMID 34650665, 2021). "In particular, ATM-derived proinflammatory cytokines, such as TNF-α and IL-1β, are similar to classically activated M1-type macrophages that directly contribute to insulin resistance or type 2 diabetes." (PMID 33794740, 2021). "Administration of a soluble TNFα receptor lead to TNFα neutralization, improving insulin-resistance." (PMID 33805912, 2021). "Among the pro-inflammatory cytokines, tumor necrosis factor-alpha is one of the most important pro-inflammatory mediators involved in developing insulin resistance." (PMID 34299261, 2021). "By controlling fasting blood glucose, reducing fasting insulin level and improving insulin resistance, tumor necrosis factor (TNF) and IL-6 levels in vivo can be significantly reduced, and inflammatory state in vivo can be significantly improved." (PMID 34531719, 2021). "The second correlation was found between lipocalin-2 and TNF-α, a predictor of insulin resistance in human pregnancy." (PMID 34769010, 2021). "IKK is activated both by TNFα in the case of peripheral insulin resistance and by Aβ in the brain, resulting in decreased neuronal insulin sensitivity." (PMID 34070553, 2021). "Though apM1 and TNF-α were considered to play critical roles on the development of insulin resistance, few studies based on general population have been designed to investigate this relation." (PMID 33997011, 2021). "Increase levels of pro-inflammatory cytokines such as IL-1β, IL-6, TNF-α and growth hormone is an important characteristic of peripheral insulin resistance." (PMID 34416903, 2021). "TNF-α has a significant effect on the insulin signaling pathways and directly contributes to insulin resistance and T2DM." (PMID 34489979, 2021). "In the present study, an insulin resistance model was established in adipocytes by incubating the cells with TNF-α." (PMID 34699329, 2021).
Insulin resistance (continued). "The improvement of WSP-EA against TNF-α-induced insulin resistance was mainly mediated by PI3K/Akt pathway." (PMID 34003397, 2021). "TNF-α elevation correlates with adipocyte dysfunction, lipolysis, and insulin resistance and is thought to play a role in systemic insulin resistance." (PMID 34162924, 2021). "Another study reported that regular exercise decreased proinflammatory cytokines, and that 6 months of moderate-intensity exercise decreased TNF-α concentration in patients with insulin resistance." (PMID 34200794, 2021). "The results with 1144 treatments are consistent with a previous study reporting that testosterone treatment inhibits JNK, IKKβ and TNFα, thus suggesting a protective mechanism of testosterone against inflammation-induced insulin resistance." (PMID 33586025, 2021). "The main mechanism by which TNF-α induces insulin resistance is by triggering post-receptor serine phosphorylation of insulin receptor substrate-1 (IRS-1) thereby interfering with the insulin signalling pathway." (PMID 33800490, 2021). "We induced metabolic imbalance using a combination treatment of TNF-α, insulin, and glucose for insulin resistance, and BSA-palmitate into cultured primary hippocampal and cortical neurons." (PMID 33859286, 2021). "TNF-α is an important pro-inflammatory cytokine that is critically involved in the development of insulin resistance and pathogenesis of type 2 diabetes." (PMID 33567531, 2021). "In cows with fatty liver syndrome, the correlation has been described between the TNF-α increase and insulin resistance and disturbed fatty acids metabolism." (PMID 34316205, 2021). "Level weight gain, visceral fat accumulation, blood lipid, TNF-α, leptin, IL-6 level reduction.Improved insulin resistance (with HOMA-IR)." (PMID 34641407, 2021). "Compared with TNFα treatment, DHM activated IRS-1 indicating that DHM ameliorated the TNFα-induced insulin resistance." (PMID 34650665, 2021). "While we found a reduction in TNF-α and other inflammatory mediators, this timeline is consistent with our findings regarding that improvement in insulin resistance precedes inflammation resolution." (PMID 34108550, 2021). "Tumour necrosis factor alpha (TNF-α) and interleukin-6 (IL-6) are the main inflammatory cytokines increased in insulin resistance and GDM." (PMID 34658643, 2021). "After low concentration horse serum on differentiation inducement of C2C12 myoblasts into mature myotubes, the cells were treated with TNF-α to induce insulin resistance." (PMID 34003397, 2021). "Circulating soluble tumor necrosis factor (TNF)-like weak inducer of apoptosis (sTWEAK) is a cytokine that regulates inflammation and insulin resistance in adipose tissue." (PMID 34764367, 2021). "TNF-α inhibits the phosphorylation of insulin receptor and its substrate, insulin receptor substrate-1, thus, promoting insulin resistance." (PMID 34652617, 2021). "Studies have shown that IL-6 and TNF-α are secreted from infiltrated macrophages into adipose tissue and have critical roles in MetS, insulin resistance, nonalcoholic fatty liver disease, and atherogenesis." (PMID 34938803, 2021). "The L14 extract treatments exhibited a significant reduction in TNF-α protein expression, which is a key factor of insulin resistance in adipocytes." (PMID 33954196, 2021). "TNF has the ability to lower insulin receptor expression that contributes to the development of insulin resistance." (PMID 33363197, 2020). "Work presented by Gonzalez-Cantero and colleagues showed that hepatic triacylglyceride content were correlated with insulin resistance and these relationships were independently to the inflammatory marker TNFα." (PMID 32709069, 2020). "Inflammatory markers, such as the pro-inflammatory cytokines TNF-α and IL-6, are the major contributor to local and systemic insulin resistance." (PMID 31829413, 2020).